RNU6-781P (RNA, U6 small nuclear 781, pseudogene)
Gene: Small nuclear RNA gene on chromosome 12 (6,709,452 to 6,709,552, forward strand). Ensembl gene ENSG00000252186.
Homologues: Orthologues: chimpanzee U6 (96% identical), rat LOC120099411 (61% identical), mouse Gm24185 (60% identical), mouse Gm23901 (56% identical), guinea pig U6 (48% identical). Paralogues in human: RNU6-46P (73% identical), RNU6-831P (73% identical), RNU6-1145P (72% identical), RNU6-188P (72% identical), RNU6-74P (72% identical), RNU6-891P (72% identical), RNU6-10P (71% identical), RNU6-1252P (71% identical), RNU6-1316P (71% identical), RNU6-15P (71% identical), RNU6-35P (71% identical), RNU6-616P (71% identical), and 1285 more.